MMP9 (matrix metallopeptidase 9)
Diseases named in the same sentence as MMP9 in open-access papers (continued):
Sharing a sentence is not in itself a finding about the gene and the disease.
tumor (continued). "Further, the gene expression profiling of the tumour exhibited a higher level of EPCAM, CK20, KRAS, AKT1, BRAF and CD133 expression, while lower levels of expression were observed in NANOG, MMP9 and APC genes." (PMID 33092235, 2020). "Cannabinoids also curtail tumor invasion and metastasis by inhibiting the secretion of matrix metalloproteinase (MMP)-2 and MMP-9, while increasing the tissue inhibitors of MMP-1 (TIMP-1)." (PMID 33066359, 2020). "ZEB1 in TAMs, a TGF-β downstream transcription factor, induces the expression of CCR2, MMP9, and CCL2 in cancer cells to accelerate tumor growth." (PMID 33224886, 2020). "Metalloproteinases (MMPs) play a critical role in promoting tumor cell migration, extracellular matrix degradation and tumor distant metastasis, among them MMP2 and MMP9 are closely related to the proliferation, invasion and metastasis of ESCC." (PMID 32913452, 2020). "It has been found to have anti-tumor effect by suppressing ERK-AP-1 and AKT-NF-kB dependent MMP-9 activity." (PMID 33520928, 2020). "In contrast, protumor neutrophils can release matrix metalloproteinase 9 (MMP9), which promotes angiogenesis and dissemination of tumor cells, and they can also suppress NK cell function." (PMID 33178577, 2020). "Matrix metalloproteinase 9 (MMP9), a member of matrix metalloproteinase (MMP) family, has been widely reported to engage in the degradation of extracellular matrix, resulting in tumor invasion." (PMID 31949487, 2020). "The co-delivery system was actively targeted and concentrated in the tumor tissue through the tumor-targeting peptide tLyP-1 sequence in K14, and then the CPLGIAG peptide was enzymolyzed by MMP9, and CUR was released, downregulating the expression of P-gp." (PMID 32512936, 2020). "To further determine the mechanism of activated fibroblasts on tumor invasion, we performed qRT-PCR to detect the expression levels of five genes (ICAM-1, VEGF-C, MMP2, MMP3, and MMP9) that were reported to be involved in ESCC invasion." (PMID 32637576, 2020). "An interesting study showed that the downregulation of Notch 4 disrupted VM network formation and inhibited the invasion and migration of tumor cells by inhibiting the activation of MMP-2 and MMP-9 in HCC." (PMID 32169087, 2020). "Some studies suggest that RUNX2 has the ability to transactivate its downstream target genes, such as MMP9, MMP13, VEGF, survivin, and IL-8, which are involved in tumor progression, invasion, and metastasis." (PMID 33313404, 2020). "Highly aggressive tumor cells express high levels of MMPs (MMP-1, MMP-2, and MMP-9), and the 5γ2 chain of laminin." (PMID 32169087, 2020). "Matrix metalloproteinase 9 (MMP9) and Vimentin play a crucial role in mediating migration and invasion processes, resulting in accelerated tumor metastasis." (PMID 32626749, 2020). "In a murine xenograft model, tumor size and angiogenesis were significantly potentiated in mice overexpressing CYP4A11 through upregulation of VEGF-A and matrix metallopeptidase-9 (MMP-9)." (PMID 32581794, 2020). "After treatment, the serum tumor marker levels along with serum MMP-2, MMP-9 and CD8+ levels in the test group decreased more remarkably, while CD4+ and CD4+/CD8+ levels increased more significantly than those in the control group (P < 0.05)." (PMID 33176740, 2020). "It exhibited a suppressive effect on tumor angiogenic factors including vascular endothelial growth factor (VEGF) and MMP-9." (PMID 32028721, 2020). "In the present study, compound 9 markedly suppressed the expression of MMP-2 and MMP-9 stimulated by VEGF in HUVECs, indicating that it reduced MMP expression in both ECs and tumor cells." (PMID 32751120, 2020). "To further confirm the role of MMP-9 in OSCC cells in vivo, we established a novel human OSCC model in zebrafish by implanting tumor cells into the yolk sac of the embryo." (PMID 32382550, 2020).
tumor (continued). "In turn, stimulated MSCs enhance the expression by cholangiocarcinoma tumor cell lines of CCR5, MMP2 and MMP9, migration, and metastasis formation in tumor xenografts." (PMID 32630699, 2020). "CD147 can stimulate tumor cells to produce MMPs, specifically MMP-2 and MMP-9, especially in metastatic tumor cells." (PMID 33178600, 2020). "In a cohort of 299 GC patients, the expression of MMP-2, MMP-9, and VEGFA positively correlated with the tumor size, invasive depth, lymphatic and venous invasion, lymph node metastasis and staging." (PMID 32456248, 2020). "Tumor-infiltrating neutrophils secrete large amounts of MMPs and growth factors, such as MMP9 and VEGF, to promote proliferation, invasion, and metastasis of tumor cells." (PMID 32993787, 2020). "It has been found that the fragments released by MMP-2 and MMP-9 cleavage of SCUBE3 can bind to transforming growth factor-b (TGF-b) type II receptors, thus activating TGF-b signal transduction to promote tumor progression." (PMID 32322168, 2020). "Heavy ion beams can exert anti-tumor effects by upregulating the pro-apoptotic gene BAX and inhibiting the anti-apoptotic gene BCL2, which inhibits MMP2 and MMP9 expression and angiogenesis in tumors." (PMID 33330321, 2020). "Further studies will be needed to unravel the mechanisms by which MMP9 drives CD44 mediated invasion and tumour progression." (PMID 32445177, 2020). "The main mechanism by which CAFs promote the progression of CCA is to support the proliferation and survival of tumor cells through the expression of cytokines and growth factors, such as periostin, thrombospondin-1, SDF-1, MMP2, MMP9, and IL-1β." (PMID 32539768, 2020). "In the favorable ccrcc2_3 subtypes, miR-204-5p was strongly upregulated, predicted long OS, and repressed several targets that are involved in tumor invasiveness and metastasis (MMP3, MMP9, AURKB, FBN2, ITGB4, SPDEF)." (PMID 32915890, 2020). "These included the production of MMP-9 and VEGF by the tumor cells and macrophages, respectively via the production of neutrophil extracellular traps (NETs) by TANs and MDSCs of granulocytic origin." (PMID 32664328, 2020). "Neutrophils secrete MMP9 into the TME, which contributes to angiogenesis, tumor progression, and metastasis in mouse transplantation models." (PMID 33101586, 2020). "The coculture of THP-1-derived macrophages with GC cells up-regulated CCL5, MMP2, and MMP9 in THP-1 cells, and increased tumor cell proliferation, clonogenic growth and migration." (PMID 32630699, 2020). "Matrine significantly attenuates tumor invasion, activation of MMP-9/MMP-2, Akt phosphorylation, DNA binding activity, nuclear factor-κB expression and mRNA levels of MMP-9, MMP2, EGF, and VEGFR1 in MDA-MB-231 cells." (PMID 33520928, 2020). "The overexpression of oncogenic proteins, such as Cyclin-D1, MCL-1, C-FLIP, XIAP, MMP-9, MMP-2, uPA, and VEGF, are correlated with constitutive NF-κB activity and involved in promoting tumor progression in CRC." (PMID 32429376, 2020). "According to another study, EGCG decreased MMP-2 expression through JNK signaling and inhibited MMP-7, MMP-9, and MMP-12 in tumor tissues." (PMID 33113766, 2020). "As our expectation, the protein expressions of Jagged2, Notch, MMP-2/MMP-9 and PI3K/AKT/mTOR signaling were significantly reduced by Mel treatment and further significantly reduced by silenced Notch/JAG2 in the harvested tumor mass." (PMID 32792862, 2020). "Moreover, stromal fibroblast reported to secrete MMP9, which in turn may activate tumour cells." (PMID 32445177, 2020). "MMP9 gene silencing is shown to change the expression of CD44 and significantly decreases migration and invasion of tumour cells." (PMID 32445177, 2020). "To determine the effects of chronic restraint stress and XYS on liver metastasis, we examined the expressions of TGF-β, IL-6, MMP-9 and VEGF in spleen tumours by RT-PCR and Western blot analysis." (PMID 33152259, 2020).
tumor (continued). "Neutrophils promote tumor initiation, growth, proliferation, and metastatic spreading through release of growth factors, myeloperoxidases ROS, VEGF, and MMP9." (PMID 32354198, 2020). "IL-6 promotes angiogenesis via MMP-9 activation which induces release of VEGF from cultured ECs and tumor cells and also induces expression of VEGF-R2 (KDR) on cultured ECs." (PMID 33109684, 2020). "Other neutrophil granule components such as matrix metalloproteinase-9 (MMP-9) have been described to mediate angiogenesis and tumor cell invasion via degradation of the basement membrane." (PMID 32983165, 2020). "In vitro studies show that pineal hormone affects the motility of OSCC cell lines by inhibiting MMP-9 and VEGF transcription, which are molecules known to influence tumor progression." (PMID 32499868, 2020). "POI was significantly correlated with tumour size, stage, 3-year survival, EGFR, HIF-1α, periostin, and MMP-9 (p < 0.05)." (PMID 33123565, 2020). "The results showed that LS276-THP was suitable for the detection of tumor-related MMP-2 and MMP-9 in vivo." (PMID 32259133, 2020). "Accumulating evidence indicates that DHA inhibits the expression of various genes, including VEGF, MMP-9, and COX-2, which are related to inflammation and tumor metastasis." (PMID 33381031, 2020). "To evaluate the level change of cytokine in tumor microenvironment after TGF-β blocking, we examined the metastasis chemoattractants secreted by primed neutrophils in the microenvironment, including MMP-9, IL-6, ICAM-1, and NE." (PMID 32201528, 2020). "Further, coculture studies of CCA and MSCs have shown that increased CCR5 expression by tumor cells upregulates metalloproteinases MMP-2 and MMP-9 in CCA cells and thereby promoted angiogenesis and CCA metastasis." (PMID 31921870, 2019). "The mechanism whereby MMP-2 and MMP-9 activity induces cancer angiogenesis involves the cleavage of latent TGF-β in a CD44-dependent manner, which can promote tumor growth and invasion." (PMID 31921634, 2019). "Many studies have sufficiently confirmed that restraining the expression of MMP-2, MMP-9, and VEGFA can inhibit tumor growth, metastasis and angiogenesis." (PMID 31214503, 2019). "TGF-β has been reported to contribute to tumor progression by inducing epithelial-to-mesenchymal transition, cell migration and invasion of epithelial tumor cells through stimulating MMP-2 and MMP-9 secretion into the tumor microenvironment." (PMID 31568519, 2019). "In fact, EVs released by CSCs and undifferentiated tumor cells carry several pro-angiogenic mRNAs, such as VEGF, FGF, angiopoietin 1, ephrin A3, MMP2 and MMP9." (PMID 31013896, 2019). "Activity of MMPs, such as MMP-2 and MMP-9, is essential for the degradation of extracellular matrix (ECM), which results in the migration and invasion of tumor cells." (PMID 31391858, 2019). "The invasion and metastasis of tumor cells is dependent on the degradation of the components of the extracellular matrix by MMPs, particularly MMP-2 and MMP-9." (PMID 31572058, 2019). "Two monoclonal anti-MMP-9 antibodies, AB0041 and AB0046, were shown to inhibit tumor growth and metastasis in a surgical orthotopic xenograft model of colorectal carcinoma." (PMID 31214203, 2019). "When the E:T ratio was 2:1, the expression of MMP9, MMP10 and MMP12 was also upregulated, indicating that the increase in MMP expression in the CAR-147 macrophages was related to tumour antigen stimulation." (PMID 31570753, 2019). "All these findings suggest that MMP2, MMP9, VEGF, and IL8 are critical during HOXB7-promoted angiogenesis, which in turn supports tumor growth and metastasis." (PMID 30664713, 2019). "The degradation and destruction of extracellular matrix (ECM) and basement membrane (BM) of tumor cell surface play important roles in tumor metastasis, to which MMP-2 and MMP-9 are recognized as the critical contributors." (PMID 30789971, 2019).
tumor (continued). "Marsdenia tenacissima inhibits tumor growth via the modulation of VEGF, MMP-2, MMP-9, GSH-Px, SOD, CAT, and MDA." (PMID 31341493, 2019). "In other studies, plasma levels of LCN2/matrix metallopeptidase 9 complex, MMP2, TIMP1, TIMP2 and TIMP3 were correlated to tumor size, lymph node involvement, tumor differentiation and prediction of tumor stage and T status in patients affected with HNSCC." (PMID 31014274, 2019). "Subsequent studies demonstrated that the application of anti-CD11b antibodies in human squamous cell carcinomas in mice resulted in a reduced tumor-infiltration of MDSCs (expressing S100A8 and MMP-9) and thereby increases the efficacy of radiation." (PMID 30941308, 2019). "(a) Cells positive for the indicated proteins were counted from 3 fields (200 × magnification) for each tumor sample, and MMP-2 and MMP-9 were examined using RT-PCR." (PMID 31068208, 2019). "In agreement with the increase in tumor growth in mice injected with GPC-1 shRNA PC-3 cells, MMP-9 protein expression was higher in these tumors as compared to controls." (PMID 31391540, 2019). "Matrix metalloproteinase 9 (MMP-9) is another marker that has been widely referenced in studies of cancer, due to its ability to promote tumor invasion and metastasis." (PMID 31687607, 2019). "AP-1 is not only closely related to the process of tumor proliferation, but also influences the local invasion and distant metastasis of tumors by regulating VEGF and matrix metalloproteinase 9 (MMP-9)." (PMID 30704487, 2019). "Activation of the transcription factor AP-1 upregulates the expression of MMP-9 and VEGF and promotes invasion and metastasis of tumor cells." (PMID 30704487, 2019). "Previous studies have revealed that microRNA-10b promotes the metastasis of a variety of tumor cells by regulating Bim, TFAP2C, P16, P21, E-cadherin, CD138, RHOC, RhoC, uPAR, MMP-2, MMP-9, HOXD10, etc 23-29." (PMID 31592231, 2019). "High levels of IL6 dramatically promoted tumor invasion and metastasis of murine melanoma by upregulation of transcription activity of STAT3 and production of STAT3-dependent MMP9 in tumor cells." (PMID 31680949, 2019). "We then tested the protein levels of TGF-β1, MMP9, and TIMP1 proteins, which were important for tumor metabolism and metastasis." (PMID 31244554, 2019). "Such dramatic changes in tumor cell physiology might be a consequence of NF-κB activation in iCCA and might be induced upon exposure to TNFα, where stimulation leads to increased matrix metalloproteinase (MMP9) expression, an essential enzyme for tumor invasion and metastases." (PMID 31349670, 2019). "MMP-9 is involved in angiogenesis, as it promotes the availability of vascular endothelial cell growth factor (VEGF) in malignant tumors, which boosts tumor progression." (PMID 33817161, 2019). "The tumor-related proteins TGF-β1, TIMP1, and MMP9 are partially suppressed by reversine but with different sensitivity in the three cell lines." (PMID 31244554, 2019). "Zymography elucidated the proteolytic activity of both MMP-9 and MMP-2 (both active and short molecular forms) in GZ17-6.02 treated mice as compared to control mice in the primary tumor and metastatic organs." (PMID 30899425, 2019). "Meanwhile, initial metastasis biomarkers, such as VEGF and MMP-9, revealed that combination treatments of MIP, ACA, and CDDP against highly metastatic tumor models successfully downregulated these protein levels." (PMID 31635311, 2019). "It has emerged that cyclin D2, MMP-9, and miR-204 expression are inversely correlated and that miR-204 targets cyclin D2 and MMP-9, inhibiting tumor growth in Rb." (PMID 31798638, 2019). "Neutrophils with the pro-tumor N2 phenotype possess CXCR4, VEGF, and MMP-9 markers, which facilitate tumorigenesis, promote tumor growth, stimulate angiogenesis, and mediate immunosuppression." (PMID 31681613, 2019).
tumor (continued). "The western blot assay and immunohistochemistry studies showed that the expression of MMP9, MMP2, VEGF and STAT3 in tumor and liver tissues were significantly decreased in a dose-dependent manner." (PMID 30651572, 2019). "Tumor derived OPN binds to macrophages through integrin α9β1 resulting in the overexpression of COX-2 and MMP-9 and promotes angiogenesis in melanomas." (PMID 31134198, 2019). "Our data showed that the expression of MMP-9 and MMP-2 was altered by DANCR/miR-135a-5p/KLF8 axis, which just further proved the regulatory network on tumor malignancies from the point of molecular level." (PMID 31827393, 2019). "Both alterations result in increased expression of matrix metalloproteinases including MMP-2 and MMP9 that facilitate degradation of ECM and lead to tumor invasiveness." (PMID 31467533, 2019). "Surprisingly, reverse transcription-PCR (RT-PCR) results showed that M/Ms from metastatic brains expressed both MMP3 and MMP9, whereas RFP-B16 tumor cells barely expressed MMP3 but produced low levels of MMP9." (PMID 30616691, 2019). "Matrix metalloproteinase-9 (MMP-9), gelatinase B, enhances tumor invasion and metastasis through degradation of the basement membrane." (PMID 30754643, 2019). "U. dioica extract treatment decreased miR-21 expression, which substantially reduced the overexpressed MMP1, MMP9, MMP13, vimentin and CXCR4, and increased E-cadherin in the treated tumor cell lines." (PMID 31362429, 2019). "Further evaluations of the averaged optical intensities of MMP‐9 and TGF‐β signals according to the tumour malignancy illustrated higher values in the group of high malignancy than those in the groups of medium and low malignancy (right)." (PMID 31264317, 2019). "On the other hand, gene expression of the mesenchymal transcriptional factors such as Snail13,14 and Zeb115,16 and one of the matrix degradation enzymes, matrix metalloproteinase 9 (MMP9), known to be involved in tumor progression, were also examined." (PMID 31387985, 2019). "When Salmonella is used as an antitumor agent, it inhibits not only tumor vascularization, but also prevents EMT by keeping an intact ECM via suppression of MMP-9 expressions." (PMID 31052558, 2019). "Among normal cells, inflammatory cell-derived MMP-9 promotes extravasation in combination with tumor-derived MMP-9 and endothelial cell clusters at metastatic sites are stimulated to produce MMP-9 by circulating VEGF." (PMID 30669448, 2019). "VEGF-C and MMP-9 have potential synergistic effects in Kazakh patients with ESCC, promoting early tumor invasion and metastasis." (PMID 31824776, 2019). "Notably, MMP-9 could promote the release of VEGF to promote tumor vascular formation." (PMID 31824776, 2019). "Western blot analysis revealed that the expression levels of the protein MMP-9, MMP-2 and Vimentin in tumor tissues of YFTL treatment groups were noticeably lower than that in the MC group." (PMID 30781674, 2019). "Compared with the expression of MMPs by tumor cells, MMP3 expression by M/Ms was 114.2-fold higher (P < 0.0001), while MMP9 production was only 10.9-fold higher (P < 0.001)." (PMID 30616691, 2019). "In the 4T1 mammary and LLC lung carcinoma models, enhanced expression of pro-metastatic proteins in MDSCs, such as Bv8, MMP9, S100A8 and S100A9, facilitates improved PMN formation, which supports more efficient tumor cell extravasation and proliferation." (PMID 30792719, 2019). "In general, lumican seems to be a potent agent for the inhibition of tumor progression, which is interesting given that MMP-2 and MMP-9 expression has been reported as positively altered in ALL cases." (PMID 31437251, 2019). "Studies demonstrate that phosphorylated p38 stimulates the expression of matrix metalloproteinase 9 (MMP9), which is involved in accelerating the process of tumor immune escape." (PMID 31231308, 2019).